NPC1 (NPC intracellular cholesterol transporter 1)
Diseases named in the same sentence as NPC1 in open-access papers (continued):
Sharing a sentence is not in itself a finding about the gene and the disease.
hepatocellular carcinoma (8 papers, 2024 to 2025). A malignant tumor that arises from hepatocytes. "Niemann-Pick type C1 protein (NPC1), a key regulator of intracellular cholesterol transport and a transmembrane protein, has been implicated in carcinogenesis, particularly in hepatocellular carcinoma (HCC)." (PMID 40881173, 2025). "Further, using proteomics data from hepatocellular carcinoma patient tissues, we observed a significant upregulation in the protein levels of NPC1 in hepatocellular carcinoma tissues, also significantly associated with poor patient outcomes." (PMID 39707615, 2025). "Our findings indicate that NPC1 plays a key role in regulating neutrophil recruitment within the tumor, which is a critical factor in the progression of hepatocellular carcinoma and is closely linked to poor patient outcomes." (PMID 39707615, 2025). "Our research found that the NPC1 protein, which is involved in cholesterol transport within cells, is highly expressed in hepatocellular carcinoma tissues and is associated with the progression and poor prognosis of hepatocellular carcinoma." (PMID 39707615, 2025). "In our study, utilizing the TCGA database analysis, we found that the mRNA of the intracellular cholesterol transporter NPC1 is highly expressed in hepatocellular carcinoma tissues and is significantly associated with poor prognosis in patients." (PMID 39707615, 2025). "In order to investigate the association between NPC1 and neutrophils in hepatocellular carcinoma tissues from clinical patients, we utilized the TCGA database for analysis." (PMID 39707615, 2025). "The comprehensive analysis presented herein has delineated a robust association between elevated NPC1 expression and hepatocellular carcinoma (HCC) tissues, in contrast to normal liver tissues." (PMID 40881173, 2025). "An eight-gene signature, including NPC1 which is associated with increased immune checkpoint inhibitor sensitivity, promotes hepatocellular carcinoma progression by activating autophagy and enhancing tumor cell proliferation, migration, and invasion." (PMID 39315094, 2024). "Given the active role of cholesterol metabolism in the liver, abnormalities in NPC1 function may impact the normal functioning of liver cells, thereby increasing the risk of hepatocellular carcinoma." (PMID 39707615, 2025). "Consistently, NPC1 was highly expressed in hepatocellular carcinoma (HCC) compared to normal liver tissue, and elevated NPC1 levels were linked to poorer overall survival." (PMID 41013744, 2025). "The results similarly indicated that compared to normal tissues, NPC1 expression levels are significantly higher in hepatocellular carcinoma tissues." (PMID 39707615, 2025). "In parallel, we observed an upward trend in the expression of NPC1 mRNA with the metastasis of hepatocellular carcinoma." (PMID 39707615, 2025). "The consistent upregulation of NPC1 in LIHC across different databases strengthens the evidence for its potential involvement in hepatocellular carcinoma." (PMID 40881173, 2025). "Using various sources of hepatocellular carcinoma data and immunohistochemical staining of tumor tissues, we confirmed that NPC1 is highly expressed in hepatocellular carcinoma tissues and is associated with poor prognosis in patients." (PMID 39707615, 2025). "The analysis revealed a cohort of genes that were significantly correlated with NPC1 expression in Hepatocellular Carcinoma." (PMID 40881173, 2025). "Compared to normal tissues, NPC1 expression is significantly elevated in hepatocellular carcinoma tissues." (PMID 39707615, 2025). "In summary, our findings confirm that the progression of hepatocellular carcinoma promoted by NPC1 relies on regulating neutrophil recruitment within the tumor microenvironment." (PMID 39707615, 2025). "By scoring the expression level of NPC1, the results demonstrated high expression of NPC1 in the clinical samples of hepatocellular carcinoma patients as well." (PMID 39707615, 2025).
hepatocellular carcinoma (continued). "In this study, we systematically explored the relationship between NPC1 and hepatocellular carcinoma." (PMID 39707615, 2025). "Preliminary mechanistic exploration suggests that NPC1 promotes hepatocellular carcinoma progression by facilitating the infiltration of neutrophils in the tumor microenvironment." (PMID 39707615, 2025). "Here, we demonstrate that knockout of Npc1 in hepatocytes attenuates hepatocellular carcinoma (HCC) progression in both DEN (diethylnitrosamine)-CCl4 induced and MYC-driven HCC mouse models." (PMID 39762312, 2025). "Concurrently, following neutrophil depletion, downregulating NPC1 ceased to influence hepatocellular carcinoma progression." (PMID 39707615, 2025). "Our preliminary research confirms a positive correlation between NPC1 and hepatocellular carcinoma progression." (PMID 39707615, 2025). "We then examined the expression levels of NPC1 mRNA during the progression of hepatocellular carcinoma and found that, as the cancer advanced, the expression levels of NPC1 mRNA gradually increased." (PMID 39707615, 2025). "To further explore the connection between NPC1 expression and hepatocellular carcinoma, we proceeded to evaluate the protein levels of NPC1 within hepatocellular carcinoma samples." (PMID 39707615, 2025). "Our analysis of transcriptomic and proteomic databases has identified increased mRNA and protein expression levels of NPC1, a cholesterol intracellular transporter protein, in hepatocellular carcinoma tissues." (PMID 39707615, 2025). "Using further neutrophil depletion experiments, we determined that the role of NPC1 in advancing hepatocellular carcinoma progression truly relies on neutrophils." (PMID 39707615, 2025). "To explore the relationship between NPC1 mRNA and the development of hepatocellular carcinoma, we initially analyzed the expression levels of NPC1 mRNA in normal liver tissues and hepatocellular carcinoma tissues." (PMID 39707615, 2025). "To further validate these results, we collected clinical samples from 50 hepatocellular carcinoma patients and performed consecutive sectioning and immunohistochemical staining for NPC1 and the neutrophil marker CD11b." (PMID 39707615, 2025). "In conclusion, our results demonstrate that NPC1 promotes hepatocellular carcinoma progression by mediating the accumulation of neutrophils in the tumor." (PMID 39707615, 2025). "To validate the high expression of NPC1 in hepatocellular carcinoma tumor tissues, we collected clinical samples from 50 hepatocellular carcinoma patients and performed immunohistochemical staining for NPC1." (PMID 39707615, 2025). "Background/Objectives: The Niemann–Pick C1 (NPC1) protein regulates cellular cholesterol homeostasis, which is disrupted in hepatocellular carcinoma (HCC)." (PMID 40722778, 2025). "Utilizing data from the UALCAN database on hepatocellular carcinoma, we observed a high expression of NPC1 protein in hepatocellular carcinoma tissues." (PMID 39707615, 2025). "According to the data from the TCGA database, there was a significant upregulation of NPC1 mRNA in hepatocellular carcinoma tissues compared to normal tissues." (PMID 39707615, 2025). "The high expression of NPC1 ultimately promotes hepatocellular carcinoma progression by affecting the infiltration of neutrophils in the tumor microenvironment." (PMID 39707615, 2025). "The results showed that the expression level of NPC1 was significantly positively correlated with the infiltration of neutrophils in hepatocellular carcinoma tissues." (PMID 39707615, 2025). "Although NPC1 is essential for cholesterol transport, its role in hepatocellular carcinoma progression is not well understood." (PMID 39707615, 2025). "To corroborate these findings, we performed immunohistochemical staining of NPC1 on liver tissue samples from patients, revealing significantly higher expression levels of NPC1 in hepatocellular carcinoma tissues compared to normal tissues." (PMID 39707615, 2025).
hepatocellular carcinoma (continued). "Our findings demonstrate that NPC1 is capable of enhancing the infiltration of neutrophils within the hepatocellular carcinoma tumor microenvironment, and the infiltration of neutrophils is positively correlated with the poor prognosis of patients." (PMID 39707615, 2025). "In summary, our findings suggest that the high expression of NPC1 mRNA in hepatocellular carcinoma tissues holds significant implications." (PMID 39707615, 2025). "In summary, our results indicate that NPC1 protein is highly expressed in the tumor tissues of hepatocellular carcinoma." (PMID 39707615, 2025). "This outcome suggests that NPC1 might advance the progression of hepatocellular carcinoma by encouraging the recruitment of neutrophils." (PMID 39707615, 2025). "Subsequently, to explore whether the progression of hepatocellular carcinoma promoted by NPC1 is dependent on neutrophil recruitment, we conducted in vivo neutrophil depletion experiments." (PMID 39707615, 2025). "This suggests that the modulation of neutrophil recruitment by NPC1 could be a significant factor in the progression of hepatocellular carcinoma." (PMID 39707615, 2025). "Overall, our findings indicate that the high expression of NPC1 could contribute to hepatocellular carcinoma progression by promoting neutrophil infiltration." (PMID 39707615, 2025). "Moreover, through using the Proteinatlas database, we further confirmed the elevated expression of NPC1 in hepatocellular carcinoma tissues, reinforcing our earlier findings." (PMID 39707615, 2025). "The results indicated that, whether alone or in combination, high expression of NPC1 and CD11b was significantly positively correlated with poor survival in hepatocellular carcinoma patients." (PMID 39707615, 2025). "The results imply that NPC1 could facilitate the advancement of hepatocellular carcinoma via the tumor microenvironment." (PMID 39707615, 2025). "NPC1 may promote hepatocellular carcinoma progression by facilitating the infiltration of immunosuppressive cells in the tumor microenvironment." (PMID 39707615, 2025). "Therefore, the high expression of NPC1 may promote hepatocellular carcinoma progression by facilitating the infiltration of neutrophils in the tumor microenvironment." (PMID 39707615, 2025). "In conclusion, our research suggests that NPC1's overexpression could contribute to hepatocellular carcinoma progression by promoting neutrophil recruitment, positioning NPC1 as a promising new biomarker and therapeutic target for hepatocellular carcinoma." (PMID 39707615, 2025). "Here, we identify a pro-tumorigenic function for NPC1 in hepatocellular carcinoma (HCC) using transgenic mice with Npc1 deletion in hepatocytes." (PMID 39762312, 2025). "However, the exact role and mechanisms by which NPC1 might regulate the onset and progression of hepatocellular carcinoma are still unclear." (PMID 39707615, 2025). "Here the authors report that NPC1 prevents ubiquitylation and degradation of TGF-β receptor 1, leading to activation of the TGF-β pathway and hepatocellular carcinoma progression." (PMID 39762312, 2025). "Subsequent investigations have revealed that NPC1 expression does not influence the proliferation of hepatocellular carcinoma cell lines in vitro." (PMID 39707615, 2025). "Drawing on previously published data, we observed that NPC1 is significantly upregulated in hepatocellular carcinoma (HCC) tumor tissue compared to nontumor tissue." (PMID 39707615, 2025). "Subsequent investigations have revealed that NPC1 expression does not significantly influence the proliferation of hepatocellular carcinoma cells in vitro." (PMID 39707615, 2025). "As NPC1 itself does not significantly affect the growth of hepatocellular carcinoma tumor cells, implying that NPC1 in tumor cells might influence the progression of hepatocellular carcinoma via the tumor microenvironment." (PMID 39707615, 2025).
hepatocellular carcinoma (continued). "Compared to negative control (shNC), NPC1 knockdown significantly suppressed cell growth in MM (ARP-1), hepatocellular carcinoma (HepG2) and ovarian cancer (SKOV3) cells in vitro." (PMID 41013744, 2025).
COVID-19 (7 papers, 2020 to 2025). A disease caused by infection with severe acute respiratory syndrome coronavirus 2. "Together, these findings warrant further research on NPC1, anti-NPC1 IgG, and antithyroid antibodies in COVID-19." (PMID 39414823, 2024). "Based on the role of cholesterol and late endosomes in SARS-CoV-2 infection, NPC1 was proposed as a therapeutic target for COVID-19 during the early time of this pandemic." (PMID 38167417, 2024). "Studies have also shown that compared with controls, the lung tissue of patients who died of COVID-19 had upregulated expression of proteins such as NPC1/2, CEACAM1, CTSL, EIF4E, and PABPN1, which involve virus-binding receptors, proteases, host mRNA degradation, and translation cessation." (PMID 38752128, 2024). "Likewise, it raises the question of the effectiveness of perturbing cholesterol trafficking with inhibitors such as U18666A targeting the host factor NPC1 in COVID-19 patients as previously proposed." (PMID 33574281, 2021). "By accurately screening and validating the role of NPC1 in ACE2 secretion, we provide insights into the molecular mechanism by which high cholesterol upregulates ACE2 levels and offer new perspectives for the prevention and treatment of coronavirus disease 2019." (PMID 40812417, 2025).
Fabry disease (7 papers, 2016 to 2025). Fabry disease (FD) is a progressive, inherited, multisystemic lysosomal storage disease characterized by specific neurological, cutaneous, renal, cardiovascular, cochleo-vestibular and cerebrovascular manifestations. "TRPML1 signaling or TRPML1‐mediated Ca2+ release is similarly impaired in other LSDs such as Niemann–Pick type C1 (NPC1), Niemann–Pick type A (NPA; also called infantile neurovisceral form of acid sphingomyelinase (SMPD1) deficiency), and Fabry disease." (PMID 35929194, 2022). "In this study, we assessed the effect of BK agonist, NS1619 and NS11021 in a number of LSDs including NPC1, mild cases of mucolipidosis type IV (ML4) (TRPML1-F408∆), Niemann-Pick type A (NPA) and Fabry disease." (PMID 27670435, 2016). "We found that upregulating BK rescued the phenotypes of patient fibroblasts from NPC1, F408∆-ML4, NPA and Fabry disease by promoting lysosomal Ca2+ release and subsequent lysosomal exocytosis." (PMID 27670435, 2016). "Reduced basal mTOR activity has also been observed in diverse models of lysosomal diseases including Neuronal Ceroid Lipofuscinosis type 3 lymphoblastoid cells, in NPC1- and NPC2-knockdown endothelial cells, in a Drosophila model of mucolipidosis IV, and a human podocyte model of Fabry disease." (PMID 34831346, 2021). "The first link between LSDs and Parkinson’s disease (PD) have been demonstrated a decade ago for Gaucher disease, and then extended to others, such as Niemann–Pick type I e II (NPC1, NPC2), GM1 and GM2 gangliosidosis, neuronal ceroid lipofuscinoses and Fabry disease." (PMID 28513549, 2017).
Hepatosplenomegaly (7 papers, 2017 to 2024). Simultaneous enlargement of the liver and spleen. "The extraneuronal disease of NPC1 is clinically significant, with hepatosplenomegaly and persistent liver disease, and even liver failure, documented in NPC1 patients." (PMID 34407999, 2021). "With this information, we aimed to unravel the molecular mechanism leading to hepatosplenomegaly observed in Npc1−/− mice." (PMID 30870990, 2019). "NP-C was described more than 100 years ago by Albert Niemann as an infantile disorder with hepatosplenomegaly and neurodegeneration, but the exact function of the NPC1 and NPC2 proteins has still to be fully elucidated." (PMID 28400970, 2017). "Hepatosplenomegaly is a well-documented symptom of lysosomal storage disorders, specifically NPC1." (PMID 30870990, 2019). "Besides other symptoms, NPC1 patients develop liver dysfunction and hepatosplenomegaly." (PMID 29587349, 2018).
Batten disease (6 papers, 2017 to 2025). "These rescue effects were evaluated in MLIV, NPC1, and Batten disease patient fibroblasts and neurons derived from isogenic human iPSC models of MLIV and Batten disease." (PMID 37567876, 2023). "In summary, new data suggest that TPC2 is a promising target for the treatment of different types of LSDs such as MLIV, NPC1, and Batten disease, both in vitro and in vivo." (PMID 36139381, 2022). "A recent paper exploring the proteomic changes in microglia with another LSD, Batten disease caused by loss of CLN3, identify similar changes to those seen here, including increased TTYH3, PTTG1IP, LAMTOR3, PSAP, STARD3NL, TSPAN7, TMEM192 and NPC1." (PMID 40608809, 2025). "Another sphingolipid, sphingomyelin, accumulates in NPC1 cells, and recently it was shown that Batten disease patients might also exhibit very high sphingomyelin levels." (PMID 36139381, 2022).
cognitive deficits (6 papers, 2013 to 2024). "Accordingly, in NPC1-/- mice, an increase in the brain adenosine level obtained by inhibiting its transport inside the cells significantly improved the animal cognitive deficits while reducing Purkinje neuron loss and sphingomyelin accumulation in the liver." (PMID 35955821, 2022). "NPC disease typically results from missense mutations (70–80% cases) in the NPC1 gene, resulting in misfolding and premature degradation of the NPC1 protein, which leads to the progressive onset of neurological symptoms such as loss of motor function and cognitive impairment." (PMID 37627292, 2023). "Impairment of these events by NPC1 mutation may explain the progressive cognitive deficits in NPC patients." (PMID 31535451, 2019).
diabetes (6 papers, 2010 to 2022). "The association remained after adjustment for by age, sex, body mass index, hypertension history, cigarette smoking, Diabetes mellitus history with binary logistic regression analysis, supporting that G allele of tag SNP NPC1 was a protective factor for CHD." (PMID 20955564, 2010). "Thus, we next analyzed the effect of NPC1 haplotypes on susceptibility to diabetes." (PMID 23153210, 2012). "A genome-wide association study (GWAS) and subsequent replication studies in diverse ethnic groups indicate that common Niemann-Pick C1 gene (NPC1) polymorphisms are associated with morbid-adult obesity or diabetes independent of body weight." (PMID 26120596, 2015).
dyslipidemia (6 papers, 2011 to 2022). "In this sense, different studies have concluded on the association between NPC1 protein deficiency and metabolic features associated with the impairment of insulin signaling pathways, such as hyperleptinemia and dyslipidemia." (PMID 34579137, 2021). "In fact, Npc1+/- mice display increased adiposity and adipocyte hypertrophy; these animals also show dyslipidemia and higher plasma glucose levels compared to their wild-type litter mates." (PMID 23153210, 2012). "Somehow in contrast with these results, a recent study indicated that heterozygosity for a hypomorphic Npc1 mutation on the C57BL/6J 'metabolic syndrome' genetic background protects old male mice, but not females, from weight gain." (PMID 23153210, 2012). "Furthermore, NPC1 is the pharmacological target of ezetimibe, which is an inhibitor of cholesterol endocytosis that is widely used for treatment of this dyslipidemia; its inhibition of α-tocopherol absorption suggests the involvement of NPC1 in dietary VE uptake." (PMID 30518135, 2018). "This breeding produced a hybrid (BALB/cJ-C57BL/6J) NPC1 mouse model, for which the Npc1+/- mice were characterized with weight gain, abdominal adiposity, adipocyte hypertrophy, hepatic steatosis, plasma dyslipidemia, and impaired glucose tolerance in the absence of hyperphagia." (PMID 22043166, 2011).